MC4R (melanocortin 4 receptor)
Diseases named in the same sentence as MC4R in open-access papers (continued):
Sharing a sentence is not in itself a finding about the gene and the disease.
Obesity (continued). "This study shows evidence of sub-clinical nerve degeneration with regeneration following treatment with the GLP-1 agonist semaglutide in two children with a MC4R gene mutation and severe obesity." (PMID 38974580, 2024). "Melanocortin 4 receptor (MC4R) mutations are the commonest cause of monogenic obesity through dysregulation of neuronal pathways in the hypothalamus and prefrontal cortex that regulate hunger and satiety." (PMID 38974580, 2024). "Humans and experimental models with impaired MC4R function develop severe obesity and present an increased predisposition to comorbidities." (PMID 39876968, 2024). "A Spanish cohort study demonstrated that C-C-C haplotype at three SNP loci (rs17782313, rs17773430, and rs34114122) within the MC4R gene significantly augmented early metabolic risk factors in children with obesity." (PMID 40302954, 2024). "For instance, MC4R deficiency causes severe hyperphagia, obesity and insulin resistance in mice and humans." (PMID 39117851, 2024). "The MC4R gene encodes a G protein-coupled transmembrane receptor that is associated with an increased risk of developing obesity and diabetes." (PMID 39605770, 2024). "The melanocortin pathway in the hypothalamus regulates appetite and eating behavior and variations in the genes encoding the melanocortin-4 receptor (MC4R) have been linked to severe obesity in children." (PMID 38395939, 2024). "We show that these obesity-associated MC4R variants affect MC4R signaling differently yet lead to a comparable clinical phenotype." (PMID 38567654, 2024). "Melanocortin 4 receptor (MC4R) deficiency due to the disruption of one or both MC4R alleles has a relationship with the frequency of obesity." (PMID 38474283, 2024). "We did not have a sex stratification, and this is a serious reason to continue our research on these data especially because more research is needed to establish a definitive link between MC4R CC genotype and sex-specific obesity risk." (PMID 39203789, 2024). "In 1998 human genetic research revealed that monogenic obesity can result from mutations in the MC4R gene." (PMID 39203789, 2024). "We also show that the homeostatic defense against overfeeding-induced weight gain is unperturbed in high-fat diet-induced obesity and that MC4R deficiency extends the time it takes before body weight is recovered following overfeeding." (PMID 38331907, 2024). "Early-onset adiposity in monogenic forms of obesity has been causally linked to loss-of-function mutations in genes controlling appetite, including the melanocortin 4 receptor (MC4R)." (PMID 38281958, 2024). "Melanocortin 4 receptor (MC4R) mutations are the most common cause of human monogenic obesity and are associated with hyperphagia and increased linear growth." (PMID 38175730, 2024). "Among these, a 16-year-old patient diagnosed with severe obesity (body mass index [BMI] of 84.5 kg/m2) had two pathogenic variants in the same gene, namely p.G98R and p.C277X in the MC4R gene." (PMID 37327085, 2023). "The primary role of activated MC4R is to promote satiety and energy use; therefore, when depleted, it causes increased food intake, leading to obesity." (PMID 37937009, 2023). "Mutations in the genes encoding the MC4R, leptin, and leptin receptor are commonly reported in various populations to cause monogenic obesity." (PMID 37329217, 2023). "Loss-of-function mutations in MC4R in rodents increase food intake, reduce energy expenditure and lead to severe obesity." (PMID 36834794, 2023). "In accordance with our study, results from a meta-analysis showed a significant association of MC4R rs17782313 with an elevated risk of obesity in Caucasians following the recessive model (OR = 1.52 95% CI 1.13–2.03, p = 0.005)." (PMID 38002939, 2023). "Human mutations in the MC4R trigger obesity, and AgRP neurons are the natural antagonist of these receptors favoring increased food intake." (PMID 37082122, 2023).
Obesity (continued). "This study’s advantages include the large, population-representative cohort, which enabled us to analyze MC4R polymorphism and the eating behaviors interactions effect associated with obesity risk." (PMID 38002939, 2023). "The rs17782313 SNP is located 188 kb downstream of MC4R and has been strongly associated with the development of obesity in populations of different ethnicity and age, including children and adolescents." (PMID 36986146, 2023). "Heterozygous loss-of-function mutations in MC4R are the most common monogenic form of severe obesity in humans; Mc4r −/− mice develop obesity associated with hyperphagia and hyperleptinemia." (PMID 37064917, 2023). "Cilium removal in MC4R-expressing cells from the mouse hypothalamus phenocopied germline loss of MC4R, which is characterised by obesity." (PMID 37256063, 2023). "Melanocortin 4 receptor (MC4R) rs17782313 polymorphism has been linked to common obesity with varying influence across different populations." (PMID 38002939, 2023). "Conversely, the gain of function variants in the MC4R gene were found to be protective against obesity and negatively associated with the phenotype." (PMID 38003551, 2023). "In MC3R dysfunction, obesity presents in milder levels compared with MC4R deletion, while a coexistence of these two deficiencies has a synergic effect on increased adiposity." (PMID 36986146, 2023). "So far, numerous heterozygous mutations in MC4R linked to obesity with variable severity have been studied functionally using in vitro cell models, revealing a subset that disrupts G-protein-coupled receptor (GPCR) signaling." (PMID 38003551, 2023). "Our study results demonstrate that MC4R rs17782313 homozygous carriers are associated with a significantly higher risk of obesity in Israeli females (OR = 1.38, 95% CI 1.1–1.72, p = 0.005)." (PMID 38002939, 2023). "Compelling genetic studies conducted in both rodents and humans have demonstrated that POMC or MC4R loss of function causes obesity and is associated with increased feeding and reduced energy expenditure." (PMID 37069175, 2023). "Pathogenic variants with complete or partial loss of function in the MC4R gene are the most common cause of monogenic obesity, accounting for up to 6% of severe early-onset obesity due to monogenic obesity genes." (PMID 38003551, 2023). "One phase IIb clinical trial administered Setmelanotide to participants with obesity with heterozygous MC4R deficiency and obese controls over 28 days, observing a placebo-adjusted weight loss of 2.6 kg and 4.0 kg respectively." (PMID 37249754, 2023). "In our study we investigated the association of polymorphisms of the FTO rs9939609 and MC4R rs1778231 genes, which have been well-documented to be related to a higher prevalence of overweight and obesity." (PMID 38066615, 2023). "MC4R expression is affected differently by each mutation, and the obesity phenotype is determined by variable penetrance, expressivity, and allelic heterogeneity that contributes to different pathogenic mechanisms." (PMID 38002939, 2023). "Even though these MC4R gene polymorphisms are related to characteristics of obesity, it is compelling how the various SNPs seem to have different impacts on the carrier’s metabolism." (PMID 37508717, 2023). "This meta-analysis evaluated the efficacy and safety of setmelanotide for weight loss in severe obesity linked to human MC4R deficiency." (PMID 37888071, 2023). "For patients diagnosed with obesity, the most common pathogenic variants were detected in the MC4R gene, which were identified in four patients." (PMID 37327085, 2023). "In this case report, we describe the therapeutic journey of a patient with early-onset obesity and hyperphagia due to a pathogenic heterozygous melanocortin-4 receptor gene variant." (PMID 36876127, 2023).
Obesity (continued). "Several studies have shown that MC4R rs17782313 SNP carriers have an increased risk for obesity among different populations, though with varying influence across different populations." (PMID 38002939, 2023). "In this study, we performed clinical, genetic, and biochemical investigations of two patients in Qatar who exhibited pronounced early-onset obesity due to novel variants in the MC4R gene." (PMID 38003551, 2023). "Variants in MC4R were the most common cause of obesity in our cohort (19%) and the c.485C>T p.T162I variant was the most frequent MC4R variant seen in 5 patients." (PMID 37329217, 2023). "We demonstrate that chronic inhibition of arcuate neurons expressing proopiomelanocortin (POMC) or paraventricular hypothalamic neurons expressing melanocortin receptor 4 (MC4R) causes massive obesity." (PMID 37069175, 2023). "MC4R and PGC1α play critical roles in energy homeostasis, and are implicated in the pathogenesis of metabolic diseases including obesity, diabetes, hepatic steatosis and CVD." (PMID 37621650, 2023). "Here, we find that the central mechanism of MRAP2-associated obesity is the critical role for MRAP2 in targeting MC4R to cilia." (PMID 36692018, 2023). "The association of MC4R rs17782313 carriers with elevated obesity risk follows different inheritance models in different studies’ findings." (PMID 38002939, 2023). "Heterozygous loss-of-function mutations in MC4R are found in 5%–6% of patients with severe early onset obesity and at a frequency of approximately 1/330 in the general UK population, making this the commonest gene in which variants contribute to obesity." (PMID 37661743, 2023). "For example, setmelanotide, a MC4R agonist is FDA approved for treatment of monogenic obesity related to POMC deficiency, leptin receptor (LEPR) deficiency, and Bardet Biedl syndrome." (PMID 37780616, 2023). "A subset of MC4R variants, identified in the UK Biobank, caused a gain in receptor function, and are associated with significantly lower BMI and lower odds of obesity, type-2 diabetes and coronary artery disease." (PMID 36943057, 2023). "The MC4R rs17782313 homozygous genotype significantly interacted with eating behaviors to enhance the risk of obesity." (PMID 38002939, 2023). "MC4R is involved in the formation of satiety, and point mutations in MC4R can induce obesity in animals." (PMID 37239994, 2023). "MC4R mutations in humans are the most common cause of severe early-onset obesity (up to 6% of early-onset obesity cases before 10 years of age), suggesting a crucial role of the central melanocortin system in the maintenance of energy homeostasis." (PMID 36834794, 2023). "The most common monogenic form of obesity is caused by mutations in the melanocortin-4 receptor (MC4R) gene (OMIM*155541)." (PMID 37375686, 2023). "In a study of 25 obese Guadeloupean patients, 5 heterozygous variants in 4 monogenic obesity genes (MC4R, NTRK2, SH2B1, and SIM1) were detected with a prevalence of 10%." (PMID 37329217, 2023). "This MC4R variant explained the early-onset obesity, hyperphagia, increased fat mass and fat-free mass, and the mild fasting hyperinsulinemia." (PMID 36876127, 2023). "Accepted genetic models were tested to determine the association of the MC4R rs17782313 SNP with obesity risk." (PMID 38002939, 2023). "We aimed to study MC4R rs17782313 and its interaction with eating behaviors on obesity predisposition in the Israeli population." (PMID 38002939, 2023). "The meta-analysis demonstrates that the C allele of the MC4R rs17782313 polymorphism confers a higher risk of obesity and hyperglycemia, and the PGC1α rs8192678 polymorphism is weakly correlated with glucometabolic disorder." (PMID 37621650, 2023). "Our findings demonstrate that MC4R rs17782313 homozygous female carriers are significantly predisposed to obesity amplified by eating behaviors." (PMID 38002939, 2023).
Obesity (continued). "MC4R agonistic action stimulates an appetite-reducing effect and is an ideal therapeutic target in individuals with obesity (who have MC4R gene mutations)." (PMID 37937009, 2023). "Of note, a sizable proportion of the human population with monogenetic obesity have genetic mutations in the melanocortin pathway; MC4R mutations are the most common form of monogenetic obesity." (PMID 37069175, 2023). "The first evidence supporting the association of MC4R with obesity was seen in mice in 1997 and subsequently in humans in 1998 by two independent groups." (PMID 38003551, 2023). "FTO rs9939609 (AA +TT) carriers and near MC4R rs17782313 (CC+TT) had a significantly higher BMI, and were associated with categorial obesity." (PMID 37664850, 2023). "Heterozygous loss-of-function (LOF) mutations in MC4R have been observed with a higher frequency in children or adults with severe obesity." (PMID 37888071, 2023). "In summary, our findings indicate that carrying the minor C allele in the combination of the genetic variants rs17782313, rs17773430, and rs34114122 of the MC4R gene is associated with an increased risk of obesity and carbohydrate metabolism alteration." (PMID 37508717, 2023). "A cross-sectional study among psoriatic patients of Romanian descent focusing on MC4R gene polymorphisms showed a significantly increased risk of obesity, diabetes mellitus and psoriatic arthritis." (PMID 36980866, 2023). "The relationships between the hypothalamic receptor gene MC4R and the development of disorders classically associated with obesity, even at a very early age, have been described in several studies." (PMID 37508717, 2023). "MC4R rs17782313 significantly predisposes to elevated obesity risk under the recessive and additive models (OR = 1.38, 95% CI: 1.1–1.72, p = 0.005 and OR = 1.1, 95% CI: 1.01–1.2, p = 0.03, respectively) adjusted for confounders (age, sex, T1DM, and T2DM)." (PMID 38002939, 2023). "Variation in the MC4R gene variants, which are responsible for encoding the melanocortin 4 receptor, is the most common genetic cause of human obesity, and obesity itself is independently associated with depression." (PMID 37072742, 2023). "Consistent with the published data from rodents and humans, chronic loss of function of POMC or MC4R neurons results in massive obesity." (PMID 37069175, 2023). "MC4R is expressed in districts, such as the hypothalamus, as well as in adipocytes, but its deficiency in mice leads to obesity with a framework that includes hyperphagia and hyperinsulinemia." (PMID 37375686, 2023). "Some genetic alterations in specific molecules, especially in children, can lead to obesity, such as those affecting leptin, pro-hormone convertase 1/3, congenital melanocortin-4 receptor deficiency, and GNAS gene mutations." (PMID 38139229, 2023). "More than 200 MC4R variants have been identified over the past two decades, inherited primarily in an autosomal dominant pattern, with obesity resulting from only one affected allele mutation." (PMID 38002939, 2023). "Leptin analogs and MC4R agonists are novel therapies that target genetic or hormonal causes of obesity." (PMID 37937009, 2023). "Another study in Brazil showed a significant (p = 0.038) increased risk for obesity of the MC4R rs17782313 carriers only in females." (PMID 38002939, 2023). "The meta-analysis of GWAS results among large population of European origin proved an association between common genetic variants in proximity to MC4R gene and fat mass, body weight and early-onset severe obesity." (PMID 36980866, 2023). "Deleterious mutations truncate or alter protein function in any of the genes along the leptin-melanocortin pathway, including MC4R, often causing early onset and severe monogenic obesity." (PMID 38002939, 2023).
Obesity (continued). "In conclusion, the C allele of the rs17782313 polymorphism near MC4R confers a higher risk of obesity and hyperglycemia, and the A allele of the rs8192678 polymorphism is associated with glucometabolic disorder in some specific populations." (PMID 37621650, 2023). "Our results, in coherence with other studies of the MC4R gene, support the relationships between this hypothalamic receptor and the development of impairments classically associated with obesity, even at a very young age." (PMID 37508717, 2023). "Over 150 different variants in the melanocortin-4 receptor (MC4R) gene that lead to impaired receptor function have been identified, which constitute the most common cause of monogenic obesity." (PMID 38027204, 2023). "Mutations in the MC4R gene (MC4R) display the most common cause of monogenic obesity and affect 2-4% of severely obese individuals." (PMID 37025415, 2023). "There were many more studies in the literature reporting the effect of the rs17782313 polymorphism on obesity risk compared to several MC4R exonic polymorphisms such as V103I, I251L, S127L and K73R." (PMID 37621650, 2023). "The most common form of monogenic obesity is caused by a mutation of the gene MC4R, a gene responsible for suppression of the perception of appetite." (PMID 37629396, 2023). "The authors propose that defects in ciliary localisation of MC4R lead to loss of receptor sensitivity, inherited obesity syndromes and accounts for the high rates of obesity found in other ciliopathies." (PMID 37256063, 2023). "The MC4R gene, known as a retinoid-like gene, exhibits expression in multiple tissues and has been implicated in the regulation of obesity-related metabolic diseases." (PMID 37372438, 2023). "Recent advances in genomic research have identified several single nucleotide polymorphisms (SNPs) in genes such as FTO, MCM6, HLA, and MC4R, associated with obesity." (PMID 38035352, 2023). "Over 150 mutations, including frameshift, nonsense, and missense, in the MC4R gene are implicated in obesity." (PMID 37937009, 2023). "On the other hand, gain-of-function mutations in MC4R protect from obesity and its cardiometabolic comorbidities, possibly through a signaling bias toward β-arrestin recruitment, causing an increased MC4R expression in the cell surfaces." (PMID 36986146, 2023). "These gain-of-function MC4R variants are associated with substantial protection from obesity and type 2 diabetes, with a 50% reduction in risk in homozygous variant carriers." (PMID 37661743, 2023). "Although MC4R mutations are the leading monogenic cause of obesity, generating MC4R agonists for general obesity treatment has been challenging due to MC4R's location and function in the CNS." (PMID 37937009, 2023). "At the same time, urban living environments were demonstrated to interact with MC4R gene polymorphisms to increase obesity traits." (PMID 37664850, 2023). "The melanocortin 4 receptor (MC4R) gene variants were the most common cause of monogenic obesity in our cohort." (PMID 37329217, 2023). "Our results show that setmelanotide (MC4R agonist) is associated with significant weight loss, body measurement, and hunger improvements in individuals who undergo treatment for obesity, and it is considered a safe drug with manageable adverse effects." (PMID 37888071, 2023). "The potentially significant SNP (SSC1_160773437) identified in the meta-analysis assay was annotated as being within the MC4R gene, which has also been associated with obesity." (PMID 37372438, 2023). "Setmelanotide is the first approved anti-obesity drug for the treatment of rare genetic conditions associated with obesity and binds to MC4R with high affinity." (PMID 36943057, 2023). "The design of the foods and testing conditions followed a previous study which demonstrated differences in fat preference between healthy participants and participants with obesity related to mutations in the Melanocortin-4-receptor." (PMID 37845034, 2023).